SPHK1 (sphingosine kinase 1)
Diseases named in the same sentence as SPHK1 in open-access papers (continued):
Sharing a sentence is not in itself a finding about the gene and the disease.
cancer (continued). "Multiple independent studies have examined the effects of SPHK1 overexpression or depletion via RNA interference (RNAi) approaches in different cancer models and have uniformly established that SPHK1 possesses a role in promoting cancer cell growth and inhibiting apoptosis." (PMID 34820423, 2021). "It has been shown that SphK1 could suppress apoptosis of cancer cells." (PMID 35201458, 2021). "Thus, SPHK1/S1P axis regulation became one of the main targets in cancer treatment." (PMID 34502095, 2021). "No mutations linked with cancer have been identified in SphK1." (PMID 32456134, 2020). "Although specific functions for each of the SphK1 isoforms have yet to be identified in vitro and in vivo we have some evidence to suggest unravelling the individual and common or overlapping functions SphK1 isoforms will add further complexity to targeting SphK in cancer treatment." (PMID 28415564, 2017). "Interestingly, and contrary to the dogma that, differently from Sphka1, SphK2 is a pro-death factor, recent experimental evidence now supports a key role for this kinase in promoting cell survival and proliferation, much like SphK1 does in cancer cells, or even in cardiomyocytes." (PMID 28878674, 2017). "Anti-intuitively, despite increased S1P levels in these experiments, reduction of SphK2 suppressed proliferation and migratory potential of cells more effectively than SphK1 ablation indicating targeting SphK2 may have stronger anti-cancer effects in cancer therapy." (PMID 28415564, 2017). "Xia and colleagues first identified the oncogenic potential of SphK1 in 2000, and evidence supporting a key role in neoplastic survival and growth has come from SphK1−/− mouse models showing reduced tumor size and increased expression of hSphK1 has been reported in many different cancer types." (PMID 28415564, 2017). "Therefore, we suggest that targeting the SphK1/S1P signaling represents a strategy that could potentially be exploited in therapeutic approaches to decrease HIF-2 activity in cancer and more particularly in ccRCC." (PMID 26974204, 2016). "Thus, it is plausible that the increase in expression of SphK1 on stiff substrate may be a critical property of a metastatic cancer cell for facilitating the cell-matrix adhesion." (PMID 26877098, 2016). "Indeed, we previously identified SphK1/S1P signaling as a new canonical modulator of HIF-1 activity under hypoxic conditions owing to a decreased proteasome degradation of HIF-1α subunit mediated by the Akt/GSK3β pathway in various cancer cell models." (PMID 25915662, 2015). "In addition, SphK1 plays a critical role in motility and invasion of some cancer cells." (PMID 24279510, 2013). "Accumulating evidences have indicated that SPHK1 could protect cancer cells from apoptosis." (PMID 21625639, 2011). "Therefore, understanding the molecular mechanisms that mediate the anti-apoptotic effect of SPHK1 may lay a foundation for new anti-cancer strategies." (PMID 21625639, 2011). "qRT-PCR results revealed upregulation of SPHK1 and FPR2 in cancer tissues, whereas FCGR2B and VSIG4 were downregulated." (PMID 41150752, 2025). "The qRT-PCR data revealed significantly higher expression levels of SPHK1 (p < 0.01) and FPR2 (p < 0.05) mRNAs in CRC tissues compared to normal tissues, whereas the expression levels of FCGR2B mRNA were obviously lower in cancer tissues (p < 0.01)." (PMID 41150752, 2025). "MiR-hsa-125b-5p affects cell proliferation, migration, and invasion by targeting multiple tumor suppressor genes such as CD147 and TPD52, and it participates in cancer progression by targeting STAT3, BMPR1B, VEGFA, SphK1, CDKN2A, and Sema4D." (PMID 41361055, 2025). "SPHK1 inhibitors, such as RB-005 and SK1-I, have been developed for the treatment of inflammatory diseases and cancers." (PMID 39769404, 2024).
cancer (continued). "We evaluated all publicly available SphK1 inhibitors and their inhibition activity using molecular docking and how SphK1 inhibitors reduce the production of S1P and might reduce chemoresistance, an approach that might be vital in the course of cancer treatment and prognosis." (PMID 38419070, 2024). "Thus, suppression of SphK1 might enhance the sensitivity of several drugs against cancer." (PMID 38419070, 2024). "Therefore, targeting SPHK1 may represent a crucial strategy for inhibiting cancer progression." (PMID 39629135, 2024). "Correlation analysis also shows that the following histaminergic transcripts: GNA15, HRH2, MAOA, WASF2, and those related to inflammation: AEBP1, CXCL1, 2, 3, and 8, SPHK1, and TNFAIP6 play an important role in cancer tissue." (PMID 36902343, 2023). "In various cancer cells, HIF-1α was shown to be stabilized by the Sphk1/S1P axis involving Sphk1 catalytic activity, S1P export, and autocrine action through S1P receptors." (PMID 36984866, 2023). "We performed immunohistochemical analysis of ACAT2, SPHK1, SNED1, KPNA2, BZW2 and KIF15 in cancer and normal tissues and statistically analyzed the staining intensity." (PMID 37202800, 2023). "Blocking SPHK1 with PF543 in vivo increased T cell cytotoxicity and reduced PD‐L1 expression on cancer cells." (PMID 35289120, 2022). "Despite SPHK1 and SPHK2 are highly homologous, different subsets of SPHK execute different physiological roles in cancers." (PMID 35965565, 2022). "Collectively, these data suggest that both SPHK1 and SPHK2 play crucial roles in stimulating tumor growth and survival, supporting the importance of regulating S1P generation for cancer treatment." (PMID 35565311, 2022). "Both SphK1 and SphK2 play crucial roles in tumorigenesis and progression of NSCLC and other human cancers, mainly by regulating cell proliferation and apoptosis." (PMID 35831279, 2022). "Thus, SPHK1 expression might play a crucial role in drug resistance in these cancer cells." (PMID 33660008, 2021). "Overexpression of SphK1 inhibits apoptosis while inducing antiapoptotic proteins c-IAP2, c-IAP1, TRAF1, and Bcl-xl in cancer cells." (PMID 33920887, 2021). "Moreover, the SphK1/SphK2 product, S1P was shown to target histone deacetylases (HDAC1/2), tumor necrosis factor receptor associated factor 2 (TRAF2), human telomerase reverse transcriptase (hTERT), and NF-κB nuclear activities linked to cancer initiation and progression." (PMID 33919234, 2021). "SPHK1 and HAS2 have previously been demonstrated to be upregulated in several types of human cancer and to play an important role in tumor development and progression, including cellular motility and cellular proliferation and angiogenesis." (PMID 33506044, 2021). "Secreted by tumor infiltrating macrophages (tumor microenvironment), TNFα was suggested to activate SphK1, stimulate the expression of S1P3, and promote the development of cancer cell resistance and metastasis in a subset of TNFα-resistant cells." (PMID 33919234, 2021). "In oral SCC cells, downregulation of leucine-rich repeats and immunoglobulin-like domains 1 (LRIG1) induced the activation of EGFR-mediated SphK1 signaling to promote extracellular matrix (ECM) remodeling and cancer cell progression." (PMID 33465049, 2021). "Previous studies have reported that the expression of SPHK1 and HAS2 was elevated in a variety of malignant tumor tissues." (PMID 33506044, 2021). "Both SPHK isoforms, SPHK1 and SPHK2, are reported to be involved in regulating oncogenesis in human cancers." (PMID 32260399, 2020). "Thus, targeting SPHK1 by exosomal miR-124 may be of clinical use in cancer treatment." (PMID 33260606, 2020). "Autophagy-related genes BID, EIF4EBP1, VMP1, SPHK1, and CX3CL1 also play essential roles in other cancers." (PMID 33224313, 2020).
cancer (continued). "More specifically, SPHK1/2 KD is involved in the inhibition of IL-6 production in MCF7 cells, thus reducing cancer-mediated inflammation." (PMID 31817453, 2019). "Taken together, both SPHK1 and S1P are promising targets for the control of EMT in cancer cells and further research on their molecular mechanisms is warranted." (PMID 31027222, 2019). "In renal cell carcinoma, SPHK1 activity controlled HIF-2α expression and the S1PR antagonist FTY720 attenuated both HIF-1α and HIF-2α accumulation in several human cancer cell lines." (PMID 31379883, 2019). "This is because AKT, SPHK1, and SPHK2 are reported to be involved in cancer cell growth and resistance." (PMID 31817453, 2019). "Treatments that modulate SPHK1 expression, such as miRNA, atorvastatin, and ectopic overexpression, have confirmed that SPHK1 induces EMT in various types of cancer cell lines." (PMID 31027222, 2019). "Therefore, SPHK1/S1P signaling could be a useful target for cancer therapy." (PMID 31101115, 2019). "The anti-cancer effects of ISO were strongly correlated with the activation of apoptotic pathways, tubulin destabilization, SPHK1/2 inhibition, and Sirt1 activation." (PMID 31817453, 2019). "Compared to the extensively investigated SPHK1 isoform, the functions and mechanisms of SPHK2 in cancer remain largely elusive and the roles of SPHK2 in cancer cells are not fully understood with inconsistencies in published data." (PMID 31891125, 2018). "Hence it could not be automatically assumed that because SphK1 had been implicated these cancers that it would play a role in HCC development." (PMID 29643998, 2018). "Sphingosine kinase 1 (SK1) is a proto-oncogenic enzyme that is highly expressed in human tumours and has been shown to act as a “cancer signalling hub”." (PMID 28695300, 2017). "Increased expression of lipid kinase, sphingosine-kinase-1 (SK1), contributes to cancer progression and oncogenic transformation." (PMID 28615679, 2017). "Previous studies have shown that miR-124 inhibits cancer cell invasion and metastasis by targeting other molecules, including slug, Rac-1, SMYD3, SphK1, and ROCK1." (PMID 28270130, 2017). "Wilcoxon matched-pairs signed rank test demonstrated that SphK1 intensity and COX-2 proportion were higher in cancer than adjacent normal tissues." (PMID 28583134, 2017). "To further investigate the anti-cancer effect of FTY720 in MM, we examined SphK1, another target of FTY720 that was shown to be overexpressed in MM." (PMID 28298211, 2017). "SPHK-1 is known to regulate HIF-1α expression under hypoxia, and it is reported that SPHK-1 is a new target for cancer therapy." (PMID 28165392, 2017). "SPHK-1 activates the AKT/GSK-3β signaling pathway, which is involved in the accumulation of HIF-1α levels under hypoxia in cancer." (PMID 28165392, 2017). "In various cancers, SPHK1 mRNA was significantly higher compared to normal tissue and the bone marrow from AML patients has much higher SPHK1 gene expression controls." (PMID 29216917, 2017). "Consistently, interference with SphK1 activity by dominant-negative mutants or competitive inhibitors, as well as inhibition of S1P by mAbs or S1P receptors antagonists, could significantly reduce cell proliferation, angiogenesis, and invasion, and increased apoptosis in some cancer cell lines." (PMID 26673009, 2016). "We opted to use FTY720 because this drug exhibits pleiotropic effects on the SPHK1-S1P-S1PR axis and affects various aspect of cancer pathogenesis." (PMID 27160553, 2016). "SPHK1 signalling also activates the PI3K-Akt pathway, another major cell survival and bioenergetic signalling pathway that is constitutively activated in cancer." (PMID 24970218, 2014). "Further, several studies have shown that ectopic expression of SPHK1 can protect cancer cells against apoptosis in response to pro-apoptotic stimuli, such as treatment with TNF-α, ionizing radiation, or anti-cancer drugs, through multiple pathways." (PMID 20846391, 2010).
cancer (continued). "Both HA and SPHK1 are established in their involvement in tumour progression; however, this study is the first to demonstrate a relationship between HMW‐HA signalling and the sphingolipid pathway in cancer." (PMID 40356021, 2025). "Early broad-spectrum inhibitors such as N, N-dimethyl-D-erythro-sphingosine (DMS) inhibit SphK1/2 activity competitively, blocking S1P production and inducing cancer cell apoptosis, but their lack of subtype specificity limits clinical application." (PMID 41234914, 2025). "Furthermore, specific SPHK1 inhibitors such as PF-543 and SKI-II have shown efficacy in preclinical cancer models by modulating macrophage polarization and enhancing immune surveillance." (PMID 41150752, 2025). "IHC assays confirmed increased SPHK1 and FPR2 expression in cancer samples." (PMID 41150752, 2025). "The activation of Sphk1/S1PR may significantly change the ability of T cells to recognize and eliminate cancer cells (immunosuppressive effects)." (PMID 38698424, 2024). "The prospect of SPHK1/MMP1 knockdown combined with the anti-PD-1 therapeutic regimen represents an efficacious approach to enhance T cell-mediated anti-tumor immunity, offering a promising avenue for potential advancements in cancer therapy." (PMID 39629135, 2024). "S1P is intracellularly produced in cancer cells and non-cancer stromal cells from sphingosine by two sphingosine kinases (sphingosine kinase 1 (SphK1) and 2 (SphK2)) and then exported to the TME." (PMID 39835329, 2024). "In this study, we assessed the influence of SPHK1 and MMP1 on tumor immunity and observed that both SPHK1 and MMP1 inhibited the ability of T cells to kill cancer cells in vitro, while promoting HNSCC growth in vivo by facilitating tumor immune evasion in mice." (PMID 39629135, 2024). "RNA modification has become a focal point in cancer research, and while the role of ALKBH5 has been established in regulating endothelial cell angiogenesis via a SPHK1 dependent manner under ischemic stress, but the crosstalk between RNA modification and angiogenesis of GBM has been less explored." (PMID 38221546, 2024). "Taking into consideration the cancer development process, the following histaminergic genes stood out: GNA15, HRH1-HRH4, MAOA, WASF2, along with inflammation-related genes: AEBP1, CXCL1, CXCL2, CXCL3, CXCL8, SPHK1, and TNFAIP6." (PMID 36902343, 2023). "Membrane molecules LRRC15, ITGA11, SPHK1 and FAP could be used as therapeutic targets for CSF-targeting cancer treatment." (PMID 36744260, 2023). "As shown treatment with SKI-178 (10 μM, 24 h) failed to affect mRNA expression of SphK1 and SphK2 in pCan1 primary cancer cells." (PMID 37604912, 2023). "We demonstrated that CSFs could be potential targets for cancer treatment, and membrane molecules FAP, LRRC15, ITGA11 and SPHK1 could be used as CSFs specific targets." (PMID 36744260, 2023). "In summary, all human tissues tested were positive for SphK1 independent of tissue type, and although this RT-PCR assay is not quantitative, there was no clear difference in SphK1 expression between cancer and adjacent tissues." (PMID 36532885, 2022). "In conclusion, targeting SPHKs, particularly SPHK1 in combination with ICB, may be of interest to combine inhibition of cancer cell expansion with stimulation of anti-tumor immunity." (PMID 35163211, 2022). "S1P is produced by phosphorylation of sphingosine by two isoforms of sphingosine kinases (SphK1 and SphK2), and irreversibly degraded into hexadecenal and ethanolamine phosphate by S1P lyase (SPL), an enzyme that has been shown to be downregulated in cancer." (PMID 35158767, 2022). "Although this view has been controversial, there is no doubt that inhibition of SphK1 activity plays an important role in the treatment of cancer, inflammation and other diseases." (PMID 35335379, 2022). "In other words, cancer cells have become reliant on SphK1 expression for survival, a phenomenon termed “non-oncogenic” addiction." (PMID 36532885, 2022).
cancer (continued). "In these studies, exposure to hypoxia upregulated Sphk1 to produce iS1P, which was exported by Spns2 to allow a subsequent autocrine action via S1P1, to stabilize HIF-1/2α and thereby drive a more aggressive cancer phenotype." (PMID 35682566, 2022). "Thus, miR-506-3p can enhance the efficacy of anti-cancer drugs and can sensitize cancer cells to DNA damage by targeting RAD51, GLI3, and SPHK1." (PMID 33766100, 2021). "Despite extensive efforts have been put in mapping out the signaling network of sphingolipid rheostat in non-stem cancer cells, the specific roles of SPHK1/S1P axis in both normal and CSC biology are just started to emerge." (PMID 34820423, 2021). "As such, blockade of SphK1 and S1P3 nuclear translocation could potentially be a novel approach to control cancer cell proliferation through blockade of downstream gene expression programs." (PMID 33919234, 2021). "Cancer cell-derived CST6 enters osteoclasts by endocytosis and suppresses the cysteine protease CTSB, leading to up-regulation of the CTSB hydrolytic substrate SPHK1." (PMID 34815788, 2021). "Moreover, there are discrepant reports regarding the intracellular localization of both SphK1 and S1P3 from IHC staining of cancer tissues." (PMID 33919234, 2021). "We questioned whether apoptosis-inducing agents can influence the intracellular trafficking of SphK1 and S1P3 in cancer cells." (PMID 33919234, 2021). "Sphingosine kinase 1 (SPHK1) can phosphorylate sphingosine to form sphingosine-1-phosphate, which plays critical roles in the regulation of cancer cell proliferation and survival in different types of cancer." (PMID 34692520, 2021). "Aside from S1PR-dependent signaling pathways, SPHK1/S1P axis also facilitates cancer cell signaling without involvement of S1PRs." (PMID 34820423, 2021). "SPHK1 was mainly localized in the cytoplasm of cancer cells, and there was no SPHK1 expression in normal pancreatic tissue." (PMID 33506044, 2021). "SphK1 is over-expressed and/or hyper-activated in RCC, promoting cancer progression." (PMID 32393791, 2020). "PF-543, despite being highly selective for SphK1, lacked the desired cytotoxicity against cancer cells at pharmaceutically relevant concentrations." (PMID 32526899, 2020). "Firstly, RES may act as an inhibitor of the S1P synthesis catalyzing enzyme—sphingosine kinase 1 and, thus, affect sphingosine kinase 1 expression and cell growth of breast MCF7 cancer cells." (PMID 31159437, 2019). "Since SPHK1 and SPHK2 have equipotent effects in cancer metastasis and resistance, inhibiting these enzymes could decrease cancer cell growth and prevent cancer cell resistance." (PMID 31817453, 2019). "Our results suggest that like Rsv, ISO can modulate SPHK1 expression and activity, and that ISO could be an excellent target for anti-cancer therapy against MCF7 cells." (PMID 31817453, 2019). "WVBF could up-regulate Fas, c-EBPβ, sphingosine kinase-1 (Sphkl), TGF-β, MITF, down-regulated IL-1R, and synergistically lead to anti-inflammatory and anti-cancer effect." (PMID 31214025, 2019). "Because sphingosine kinase 1 and sphingosine kinase 2 (SPHK 1/2) are both essential for sphingosine-1-phospate production, they could be a therapeutic target in various cancers." (PMID 29208982, 2017). "Therefore, SPHK1 and SPHK2, two enzyme essential for S1P generation, as well as S1P itself and S1P receptors, have been recognized as promising targets for cancer treatment." (PMID 29208982, 2017). "Despite abundant reports strongly suggesting that S1P is associated with cancer progression, few findings obtained with a selective inhibitor of SphK1 or SphK2 however suggested that they are not involved in cell growth of cancer cells." (PMID 29269995, 2017). "There was a negative relationship between the expression levels of SphK1 and miR-124 in the three cancer cell lines." (PMID 28212569, 2017).